DSG1 (desmoglein 1)
Diseases named in the same sentence as DSG1 in open-access papers (continued):
Sharing a sentence is not in itself a finding about the gene and the disease.
melanoma (15 papers, 2016 to 2025). A malignant, usually aggressive tumor composed of atypical, neoplastic melanocytes. "Importantly, media from Dsg1-deficient keratinocytes increased melanoma cell migration in trans-well migration assays and melanoma cell migration exhibited a significant negative correlation with Dsg1 expression levels in keratinocytes." (PMID 39201498, 2024). "Loss of DSG1 in epidermal KCs may lead to melanocyte loss from the epithelium and promote invasive/metastatic growth of transformed melanocytes (melanoma), suggesting that IFE KCs “imprint” (or instruct) melanocytic behaviors." (PMID 36671405, 2022). "Therefore, this scenario highlights that Dsg1 deficiency may contribute to pagetoid behavior, such as occurring in early melanoma development." (PMID 38473275, 2024). "During early melanoma movement within its primary epidermal niche, melanoma cells inhibit Dsg1 protein in keratinocytes." (PMID 40869222, 2025). "Melanocytes in Dsg1-silenced skin equivalents delocalize suprabasally, contributing to the pagetoid behavior occurring in early melanoma development." (PMID 38473275, 2024). "The down-regulation of keratinocyte Dsg1 not only inhibits Braf-mutation-induced OIS, but also promotes melanoma cell migration activity." (PMID 37174106, 2023). "Keratinocytes are the cells that are adjacent to melanocytes, and melanomas can induce the downregulation of the Desmoglein-1(Dsg1) protein in keratinocytes by the paracrine signaling process." (PMID 37174106, 2023). "Kaplan–Meier survival analyses showed that FLG, KRT5, DSG1, DSG3, and IVL expression levels were significantly associated with melanoma patient survival (p < 0.01)." (PMID 33178610, 2020). "IPA found indirect inhibition of DSG1 by HGF in malignant melanoma highlighting that DSG1 down-regulation contributes to cell-cell adhesion disruption easing invasion." (PMID 32564264, 2020). "However, in other subtype melanoma patients, only DSG1 and PKP1 exhibit significantly elevated protein expression levels compared to adjacent normal samples, with no observed differences in other genes between tumor and adjacent normal samples." (PMID 38660305, 2024). "The restoration of E-cadherin, Dsg1, or Cx43 expression was shown to reduce melanoma growth." (PMID 39201498, 2024). "The involvement of keratinocyte Slug/Grhl1/Dsg1 pathway activation in melanoma cell movement is supported by patients’ samples analysis where keratinocyte Dsg1 and Slug were found negatively and positively correlated, respectively, to the extent of intraepidermal melanoma spread." (PMID 39201498, 2024). "Furthermore, in vitro treatment of differentiated keratinocytes with melanoma, but not melanocyte-derived conditioned media, reduced Dsg1 mRNA and protein levels in keratinocytes, indicating that melanoma downregulates keratinocyte Dsg1 through paracrine signaling." (PMID 39201498, 2024). "In vitro experiments showed that melanoma-conditioned media induce upregulation of the transcriptional repressor Slug in keratinocytes and consequently decreased the expression of the transcription factor Grainyhead like 1 (Grhl1), a transcriptional activator of Dsg1." (PMID 39201498, 2024). "A smaller tissue from patient ID 9561, collected in 2008, had four clusters, including melanoma (PMEL, TYRP1), immune cells (TMSB4X, IL32), keratinocytes (KRT10, KRT1, DSG1), and fibroblast areas (COL1A2, COL1A1, DCN)." (PMID 39846232, 2025). "As the expression levels of DSC2, DSC3, DSG1, KRT6B, PKP1, and PKP3 increased, the overall survival time of trunk subtype melanoma patients significantly decreased." (PMID 38660305, 2024). "Our analysis, grounded in WGCNA and PPI networks, identified six genes (DSC2, DSC3, DSG1, KRT6B, PKP1, PKP3) with pivotal roles in melanoma’s oxidative stress response and immune infiltration." (PMID 38660305, 2024).
melanoma (continued). "Among these hub genes, we identified the attenuated expressions of CDH1, COL17A1, DSG1, KRT14, and FLG in melanoma metastases compared with primary melanoma via bioinformatics analysis upon the GSE8401 and TCGA datasets." (PMID 35054979, 2022). "Five key genes FLG, DSG1, DSG3, IVL, and EGFR were identified in the TCGA database and melanoma tissues." (PMID 33178610, 2020). "The results indicate that in trunk subtype melanomas, the protein expression levels of DSC2, DSC3, DSG1, KRT6B, PKP1, and PKP3 are significantly higher than those in adjacent normal samples, suggesting the crucial roles of these central genes in SKCM progression." (PMID 38660305, 2024). "The results suggested that FLG, DSG1, DSG3, IVL, and EGFR might play important roles and potentially be valuable in the prognosis and treatment of melanoma." (PMID 33178610, 2020). "In contrast, expression of other desmosomal cadherins (DSG1, DSG3, DSC1, DSC2, DSC3) was negligible, revealing that DSG2 is unique within this gene family for its expression in a large proportion of melanoma cell lines." (PMID 27340778, 2016). "However, Dsg1 downmodulation seems to facilitate intra-epidermal migration, independently of any detectable reduced expression of E-cadherin, showing that melanoma epidermal spread, differently to dermal invasion, is not an indirect result of loss of this cadherin." (PMID 40869222, 2025).
allergies (10 papers, 2016 to 2025). "Dsg1 loss-of-function mutations in humans result in skin lesions and multiple allergies, and isolated patient keratinocytes exhibit increased proallergic cytokine expression." (PMID 34905516, 2022). "Patients with SAM syndrome harboring Dsg1 loss of function mutations have severe allergies, and keratinocytes isolated from those patients produce Th2 cytokines." (PMID 34905516, 2022). "Supporting this, chronic loss of Dsg1, as occurs in SAM syndrome, is associated with chronic inflammatory and allergic disease." (PMID 34905516, 2022). "As one major component of desmosome, DSG1 has been well characterized in inflammatory skin disease named severe dermatitis, multiple allergies, and metabolic wasting (SAM) syndrome." (PMID 32076408, 2019). "DSG1 dysfunction results in severe skin dermatitis, multiple allergies and metabolic wasting, i.e. the SAM syndrome, indicating that this cadherin plays a key role in maintaining epidermal barrier." (PMID 32076408, 2019). "The comparative data on desmoglein 1 function in humans suggest that the identified DSG1 variant may have caused the footpad hyperkeratosis and predisposition for allergies and skin infections in the affected dog." (PMID 32344723, 2020). "Positive staining for eotaxin-1 and negative staining for desmoglein-1, observed in patients with upper gastrointestinal symptoms and allergy who did not meet the diagnostic criteria for EoE, may suggest a subclinical course of the disease." (PMID 40284218, 2025). "Positive staining for eotaxin-1 and negative staining for desmoglein-1 in patients with esophageal symptoms and allergies but who did not meet EoE diagnostic criteria could be indicative of subclinical course of the disease or a masking effect of corticosteroids." (PMID 40284218, 2025). "The least severely affected bi‐allelic DSG1 variant carrier described in the literature to date is an Egyptian individual who presented with PPK, skin fragility, elevated IgE levels, and no history of allergies." (PMID 40878888, 2025).
Autoimmunity (10 papers, 2017 to 2025). The occurrence of an immune reaction against the organism's own cells or tissues. "Immunoglobulin G subclass analysis in PF reveals the presence of both IgG1 and IgG4 antibodies targeting Dsg1, with IgG4 being the predominant subclass involved in pathogenic autoimmunity." (PMID 40831828, 2025). "As positive controls to validate our epitomic approach, we also measured binding of PV AuAbs to the ES for Dsg1 and Dsg3 epitopes, which are well-known targets of PV autoimmunity." (PMID 40120680, 2025). "The pathogenesis of PV centres around autoimmunity due to the production of anti-Dsg1/3 autoantibodies, but also involves an interplay with T-cell responses." (PMID 39075718, 2024). "The cross-reactivity of antigens of the putative virus with the targets of autoimmunity in EPF (primarily DSG1) and epitope spreading would initiate the development of the pathologic autoimmunity characteristic of EPF." (PMID 35632621, 2022).
Palmoplantar keratoderma (8 papers, 2014 to 2025). Abnormal thickening of the skin of the palms of the hands and the soles of the feet. "This analysis identified a single homozygous private protein-changing variant in DSG1, a known candidate gene for palmoplantar keratoderma in humans." (PMID 32344723, 2020).
bullous pemphigoid (7 papers, 2020 to 2025). Bullous pemphigoid (BP) is the most common form of autoimmune bullous dermatosis. "The absence of anti‐BP180/230 antibodies, which are typically elevated in bullous pemphigoid, contrasted with elevated anti‐desmoglein 1/3 antibodies (anti‐Dsg1: 171 U/mL; anti‐Dsg3: 172 U/mL), confirming the characteristic autoantibody profile of PNP." (PMID 41179602, 2025).
psoriasis (7 papers, 2016 to 2025). An autoimmune condition characterized by red, well-delineated plaques with silvery scales that are usually on the extensor surfaces and scalp. "Consistent with the clinical importance of these findings, treatment of 2 Dsg1-deficient patients with an IL-12/IL-23 antagonist originally developed for psoriasis resulted in improvement of skin lesions." (PMID 34905516, 2022). "Indeed, CK14-Cre-driven knockout of ARPC4 leads to a psoriasis-like phenotype and a downregulation of DSG1 and DSC129." (PMID 39271654, 2024). "In the psoriasis lesional skin, high expression of desmocollin 2 (DSC2) and desmoglein 3 (DSG3) was also observed, in contrast to the low expression of desmocollin 1 (DSC1) and desmoglein 1 (DSG1)." (PMID 36841845, 2023).
eosinophilic esophagitis (4 papers, 2015 to 2025). Eosinophilic esophagitis (EoE) is a chronic, allergic disease of the esophagus characterized clinically by symptoms of esophageal dysfunction (including vomiting, dysphagia, feeding disorders, food impaction and abdominal pain) which persist after treatment with proton pump inhibitors (PPIs). "Dsg1 deficiency also contributes to an allergic disorder called eosinophilic esophagitis (EOE), which exhibits Th2 skewing, and some patients with SAM syndrome exhibit EOE as well." (PMID 34905516, 2022). "Patients with eosinophilic esophagitis are likely to present with reduced levels of desmoglein-1 in the epithelium, resulting in the disruption of epithelial integrity and weakening of the epithelial barrier within the esophagus." (PMID 40284218, 2025). "Recent data have suggested a functional role for DSG1 and its dysregulation in the pathophysiology of eosinophilic esophagitis." (PMID 26073755, 2015).
ichthyosis (4 papers, 2016 to 2025). Disorders of cornification that are characterized by visible scaling and/or hyperkeratosis of most or all of the skin. "The association between ichthyosis and lymphoma was determined based on the presence of lymphoma in a patient with congenital ichthyosis and the identification of a genetic mutation in DSG1." (PMID 39949400, 2025). "This congenital form of ichthyosis is due to mutations in the desmoglein-1 (DSG1) or the desmoplakin (DSP) gene, encoding for desmoglein-1 and desmoplakin, respectively." (PMID 35840979, 2022). "The Th17 skewing due to Dsg1 deficiency is reminiscent of recent observations that patients with ichthyosis with various underlying genetic bases, all having previously reported links to AD, showed robust Th17/IL-23 skewing." (PMID 34905516, 2022). "Our observations also raise the question of whether Dsg1 loss may be a common factor in PSO and other ichthyoses with Th17 skewing, as is the case in Netherton syndrome, in which Dsg1 is degraded due to loss of LEKTI-1 (lympho-epithelial kazal type related inhibitor type 5) function." (PMID 34905516, 2022). "The conclusion that ichthyosis is related to lymphoma rather than HIES is based on the clinical presentation of lymphoma in a patient with congenital ichthyosis and the detection of a specific genetic mutation in DSG1." (PMID 39949400, 2025).
leishmaniasis (4 papers, 2020 to 2024). Infectious disease that is transmitted through the bite of hematophagous female phlebotomine sand flies. "Circulating anti-Dsg1 autoantibodies are detected in patients with insect-borne diseases such as Leishmaniasis and Chagas disease and also in dogs and cats." (PMID 35281450, 2022). "Additionally, they showed that sera from Tunisian leishmaniasis patients exhibited high titers of anti-PpSP32 (n=56), anti-Dsg1 (n=14), and anti-Dsg3 (n=17) antibodies, which positively correlated." (PMID 35693761, 2022). "Moreover, patients with leishmaniasis, Chagas disease, and onchocerciasis frequently have anti-Dsg1 antibodies." (PMID 33108348, 2020). "The antibodies produced against antigens LJM11 and LJM17, present in the salivary glands of Lutzomyia longipalpis (sandfly, transmitter of leishmaniasis), may interact with Dsg1, due to structural similarities between these proteins, which could trigger the disease by cross-reaction." (PMID 37805349, 2024). "Interestingly, non-pathogenic anti-Dsg1 antibodies are also detected in the sera of patients with Leishmaniasis and Chagas disease." (PMID 35281450, 2022). "Since nonpathogenic anti-Dsg1 antibodies were detected in sera of leishmaniasis patients, we reasoned that while taking their blood meal in humans, L. longipalpis inoculates salivary proteins that induce cross-reactive anti-Dsg1 antibodies." (PMID 35693761, 2022).
pemphigoid (4 papers, 2019 to 2025). "Clinical observations further highlight humoral dysregulation in OLP, such as the presence of autoantibodies against desmogleins (Dsg1/3) and bullous pemphigoid antigens (BP180 and BP230)." (PMID 41200175, 2025).
pemphigus erythematosus (4 papers, 2012 to 2025). "Seborrheic pemphigus typically presents with localized lesions that respond to topical therapies, whereas this patient demonstrated widespread involvement and positive desmoglein-1 antibodies, which are more consistent with pemphigus erythematosus." (PMID 41426874, 2025). "The eosinophilic infiltration and elevated IgE observed support Th2 predominance, potentially driving B cells to produce anti-Dsg1 autoantibodies and trigger pemphigus erythematosus." (PMID 41000395, 2025). "Our present paper demonstrates that patients with pemphigus erythematosus produce both antiepithelial antibodies specific for desmoglein 1 and 3 and antinuclear antibodies specific for Ro, La, Sm, and double-stranded DNA antigens." (PMID 23320149, 2012). "In this case, widespread erosions, elevated desmoglein-1 antibodies, positive ANA, and intraepidermal acantholysis on biopsy supported the diagnosis of pemphigus erythematosus." (PMID 41426874, 2025).
squamous cell carcinoma (4 papers, 1997 to 2022). A carcinoma arising from squamous epithelial cells. "A loss of DSG1 is associated with an invasive phenotype, metastasis and decreased survival in squamous cell carcinoma." (PMID 32691230, 2021).
staphylococcal scalded skin syndrome (4 papers, 2007 to 2024). A blistering skin disorder caused by exfoliative toxins produced by Staphylococcus aureus infection. "Human desmoglein 1 ((HUMAN)DSG1) is known to be the target for the exfoliative toxins (ETs) from S. aureus involved in the disease staphylococcal scalded skin syndrome (SSSS)." (PMID 17397555, 2007).
asthma (3 papers, 2019 to 2023). "In fact, only one study so far has reported that DSG1 might be one of the key biomarkers associated with rhinovirus-induced asthma." (PMID 32076408, 2019). "In a murine asthma model, bronchial wall tissue analysis noted reduced DSG1 expression following asthma exacerbation and reduced epithelial barrier integrity, potentially predisposing to further exacerbations." (PMID 37147394, 2023). "We further evaluated the effect of YPFS on DSG1 both in the HDM-induced asthma recurrence model and the ALI culture of 16HBE cells." (PMID 32076408, 2019). "Since exposure to HDM induced irrecoverable deficiency of DSG1 in the asthma recurrence model, we further confirmed the effect of HDM on DSG1 in vitro." (PMID 32076408, 2019). "Our data not only demonstrated the pivotal role of DSG1 in asthma pathogenesis, but also provided a novel and potent therapeutic strategy against chronic asthma." (PMID 32076408, 2019). "To verify this hypothesis, we observed the dynamic changes of CLDN1, E-cadherin and DSG1 in lung tissue in different phases of asthma recurrence model, especially during the remission period." (PMID 32076408, 2019). "Finally, the correlation between the potency of YPFS against HDM-asthma relapse and DSG1 was evaluated in vivo and in vitro." (PMID 32076408, 2019). "Collectively, administration of YPFS in remission prominently alleviated HDM-induced asthma relapse by restoring DSG1 and decreasing TSLP overexpression, which might be the key factors contributing to chronic asthma relapse." (PMID 32076408, 2019). "Since DSG1 has been found to be critical for epithelial barrier, and its dysfunction leads to inflammation of skin and esophagus, we speculated that the perturbation of DSG1 might also contribute to asthma pathogenesis." (PMID 32076408, 2019). "Furthermore, YPFS could significantly inhibit asthma recurrence by restoring abnormal decreased DSG1 during remission period." (PMID 32076408, 2019). "Collectively, DSG1 contributed crucially to bronchial barrier integrity, and HDM could induce long-term deficiency of DSG1 and abnormal expression of TSLP which might result in a sensitive microenvironment at bronchial epithelium, and lead to asthma relapse upon another allergen exposure." (PMID 32076408, 2019). "We next evaluated dynamic changes of DSG1, E-cadherin and CLDN1, which are the main junction proteins of desmosome, AJ and TJ, respectively, in the airway during different phases of asthma recurrence model." (PMID 32076408, 2019). "Data showed that YPFS could significantly upregulate the expression of DSG1 and inhibit the overexpression of TSLP in remission phase of the asthma recurrence model." (PMID 32076408, 2019). "Collectively, the dysfunction of DSG1 during the remission phase might contribute to bronchial barrier compromise and overexpression of TSLP, which facilitated asthma relapse in a faster and more severe pattern." (PMID 32076408, 2019). "Most importantly, DSG1 did not restore in remission phase, indicating that DSG1 degradation might play a pivotal role in the pathogenesis of asthma recurrence." (PMID 32076408, 2019). "Univariable linear regression analyses for DSG1, DSC1 and JUP identified that a history of BPD had significant association with each of these three proteins (β−0.23, p = 0.014; β−0.27, p = 0.019; β−0.23, p = 0.008 respectively) but sex, age, diagnosis of asthma and low lung function did not." (PMID 37147394, 2023).
breast carcinoma (3 papers, 2022 to 2026). "The fact that Dsg1 binds to Erbin, which stabilizes ErbB2 in breast cancer cells, raises the possibility that Erbin stabilizes ErbB2 in the proximity of Dsg1 in the superficial epidermis." (PMID 35686051, 2022).
cervical cancer (3 papers, 2017 to 2021). A primary or metastatic malignant neoplasm involving the cervix. "During the progression of cervical cancer, from normal cervical tissues to CIN 1, 2 and 3, the gradually down‐regulated genes we confirmed were CRISP3, CRISP2, PPP1R3C, and DSG1." (PMID 33624385, 2021).